APOB (apolipoprotein B)
Diseases named in the same sentence as APOB in open-access papers (continued):
Sharing a sentence is not in itself a finding about the gene and the disease.
cancer (continued). "Previous CRC studies found that glycated apoB IHC expression increased from the normal tissue around the cancer site (18%) to the cancer tissue (45%)." (PMID 36864816, 2023). "The APOBEC3 (apolipoprotein B mRNA editing enzyme catalytic polypeptide 3) family of cytidine deaminases is responsible for two mutational signatures (SBS2 and SBS13) found in cancer genomes." (PMID 35597990, 2022). "We then excluded those diagnosed with cancer (n = 142) because of the large effect of tumors on serum apolipoprotein B and bone density." (PMID 36568987, 2022). "Smoking can also trigger apolipoprotein B mRNA-editing enzyme catalytic polypeptide-like (APOBEC) activity, a major putative enzymatic source of mutation in cancers." (PMID 36341427, 2022). "We evaluated the clinicopathological correlates of the 7 SMGs, together with 6 additional cancer genes identified from at least 2 previous HCC genomics studies and mutated in ≥3 HCCs of the current cohort (APOB, ARID2, CDKN2A, KEAP1, RB1 and TSC2)." (PMID 35508466, 2022). "Genomically, a characteristic of the IFNγ-signaturehigh basal/squamous subgroup is that the cancers carry elevated signatures of Apolipoprotein B mRNA Editing Catalytic Polypeptide-like (APOBEC) mediated mutagenesis." (PMID 36358715, 2022). "Although there have been some recent cell and animal experiments indicating that expression of the gene encoding apolipoprotein B mRNA editing enzyme catalytic subunit 3B (APOBEC3B) is closely related to cancer, it still lacks pan-cancer analysis." (PMID 35918642, 2022). "Hypermutated cancers develop as a consequence of extrinsic or intrinsic factors, such as tobacco smoke, ultraviolet light, apolipoprotein B mRNA editing enzyme (APOBEC, catalytic polypeptide-like) dysfunction, or DNA repair gene mutations." (PMID 34503126, 2021). "Several studies have showed that SERPINA1, APOA1, VCAN, and APOB mediated the development of cancer chemotherapy resistance." (PMID 34737677, 2021). "As an apolipoprotein B mRNA editing enzyme, APOBEC family has been shown to be associated with multiple cancer mutations and contribute to the variety of cancer mutation burdens." (PMID 34513841, 2021). "Participants in the second, third, and fourth quartiles of apoB had 18%, 21%, and 26% higher risks of cancer death compared with the first quartile, respectively." (PMID 31936330, 2020). "In the present study, the apoB/apoA-I ratio was superior compared with CRP for predicting cancer mortality." (PMID 31936330, 2020). "We analyzed data from 17 745 participants (mean age, 59.2±9.1 years; men, 44.9%) in the EPIC‐Norfolk (European Prospective Investigation Into Cancer in Norfolk Prospective Population Study) population study in whom apoB/apoA‐I and Lp(a) levels were measured." (PMID 31407609, 2019). "The apolipoprotein B mRNA-editing enzyme, catalytic polypeptide-like (APOBEC) mutational signature has only recently been detected in a multitude of cancers through next-generation sequencing." (PMID 29324969, 2018). "Recent studies have reported of an association between high serum apolipoprotein A1 (APOA1) levels and favorable prognosis in several malignancies, while the significance of apolipoprotein B (APOB) in cancer is less well-known." (PMID 28710487, 2017). "HPV-driven cancers share characteristic somatic changes, including apolipoprotein B mRNA editing catalytic polypeptide-like (APOBEC)-driven mutations and genomic instability leading to copy number variations and large chromosomal rearrangements." (PMID 28771191, 2017). "High APOA1 and APOB levels and low APOB/APOA1 ratio associated with improved cancer specific and overall survival." (PMID 28710487, 2017).
cancer (continued). "Apolipoprotein B mRNA editing catalytic subunit 3B (A3B), a nuclear enzyme that catalyzes cytidine-to-uridine (C-to-U) editing in single-stranded DNA (ssDNA), contributes to genetic diversity in many cancers." (PMID 41055562, 2025). "Apolipoprotein B mRNA editing catalytic subunit 3 (APOBEC3) is a cytidine deaminase that not only contributes to defense against viruses but is also a potential mutagen in several cancer types." (PMID 41055562, 2025). "Altered APOB expression may therefore shape immune cell infiltration and activity, creating conditions that either favor or hinder cancer dissemination." (PMID 41291156, 2025). "Mutations of APOB, USH2A, and KMT2D were reported to be associated with poor prognosis in several cancer types, and could be considered targets for combination therapy." (PMID 38922489, 2024). "Overall, our study sheds light on an underexplored area of research and provides valuable insights into the association between serum apoB and TT in the context of cardiovascular health in adult males without cancer." (PMID 38435750, 2024). "The cytidine deaminase, Apolipoprotein B mRNA editing enzyme catalytic subunit 3B (APOBEC3B, herein termed A3B), is a critical mutation driver that induces genomic instability in cancer by catalyzing cytosine-to-thymine (C-to-T) conversion and promoting replication stress (RS)." (PMID 37270643, 2023). "Despite the fact that 4HNE forms protein adducts with apoB to change LDL recognition, the role of apoB-4HNE in cancer progression is still unknown." (PMID 36864816, 2023). "Apolipoprotein B mRNA-editing catalytic polypeptide-like 3C (APOBEC3C), a member of the APOBEC3 subfamily, is implicated in HIV-1 restriction, with an unclear relationship to cancer." (PMID 35601497, 2022). "Apolipoprotein B mRNA-editing enzyme catalytic polypeptide-like 3 (APOBEC3) has been identified as a group of enzymes that catalyze cytosine deamination in single-stranded (ss) DNA to form uracil, causing somatic mutations in some cancers." (PMID 34638749, 2021). "Across the quartiles of apoB/apoA-I ratio in Model 1 (adjusted for age, sex, race, PIR, and education level), participants in the highest quartile (Q4) had a 62% greater risk of cancer mortality compared with the first quartile (Q1 = HR: 1.62; 95% CI: 1.38–1.78)." (PMID 31936330, 2020). "We also noticed that apoB levels might be effective in the prediction of cancer death, which was comparable with the apoB/apoA-I ratio." (PMID 31936330, 2020). "We also investigated whether CRP could affect the predictive potential of the apoB/apoA-I ratio for cancer mortality and vice versa." (PMID 31936330, 2020). "Numerous studies have indicated that ApoA-I and ApoB play a non-negligible role in malignancies, but the underlying mechanisms are not fully known." (PMID 31956353, 2020). "Five of the inherited variants in genes associated with cancer or actionable for hereditary diseases have been described in the literature as pathogenic (MUTYH: c.933+3A > C) or of unknown significance (APC, APOB, DSG2, DSP)." (PMID 30233642, 2018). "Recent study results have demonstrated that a subclass of apolipoprotein B mRNA-editing enzyme, catalytic polypeptide-like (APOBEC) cytidine deaminase may induce mutation clusters in various types of cancer." (PMID 24748981, 2014). "It has been shown that apolipoprotein B (apoB) and apoE rich lipoproteins are taken up by a receptor-mediated pathway in primary podocytes isolated from a human carcinoma kidney, and recently albumin was shown to be endocytosed by human podocytes in vitro and in vivo." (PMID 21949853, 2011). "Interestingly, WGS revealed that mutational clusters accumulated in ALB (encoding albumin) or APOB (encoding apolipoprotein B), although these were not directly associated with cancer development." (PMID 35158835, 2022). "Furthermore, the predictive value of the apoB/apoA-I, but not apoB, to detect cancer death risk was better than CRP." (PMID 31936330, 2020).
cancer (continued). "APOBEC3H is a member of the apolipoprotein B mRNA‐editing enzyme catalytic polypeptide 3 families of proteins, and it induces somatic mutagenesis in cancer cells that drive tumour evolution and may manifest clinically as recurrence, metastasis and/or therapy resistance." (PMID 33048468, 2020). "This analysis identified several hub genes, including APOH, APOB, APOA1, and APOA2, which play significant roles in cancer progression." (PMID 39399493, 2024). "APOBEC3H is a member of the Apolipoprotein B mRNA Editing Catalytic Polypeptide-like (APOBEC) family, which has been previously reported to have a significant impact on the instability of cancer genome." (PMID 38685053, 2024). "The accumulating evidence demonstrates that the apolipoprotein B mRNA editing enzyme catalytic polypeptide-like (APOBEC), DNA-editing protein plays an important role in the molecular pathogenesis of cancer." (PMID 35740493, 2022). "Moreover, ApoB-lipoproteins (VLDL, IDL, and LDL) and their components modulate intracellular metabolism and have been associated with the development of neoplastic phenomena such as proliferation, anchorage-independent growth, epithelial-mesenchymal transition, and cancer invasion." (PMID 36552834, 2022). "Genes such FAM182A, SOX9, AHNAK2, ENSG00000121031, FLT3LG, PMEPA1, ZFP36L2 in the large intestine, ALB, KRTAP19-1, APOB, CD200, CRYGD, KRTAP24-1, OR6N2 in the liver are novel predictions, and their functions in these cancers can further be studied." (PMID 34997044, 2022). "The other 6 genes, GPR98, ZFYVE26, AHNAK2, APOB, ZNF236, and ODZ1, were all supported to be related to cancers by research." (PMID 33244318, 2020). "Pan-cancer mutational signature analyses have identified a signature consisting of apolipoprotein B mRNA editing enzyme, catalytic polypeptide-like (APOBEC), which is a cytosine deaminase, in a subset of cancers, including HCC." (PMID 32670354, 2020). "In this case, the assumption made for FINC, APOB and PLTP would be the opposite: cancer cells eliminate more PIK3IP1 protein in the urine, as a mechanism to down-regulate its expression, in order to survive." (PMID 31963743, 2020). "Our model included APOAI, APOB, GGT and LDH, which are good prognostic markers in different types of cancers." (PMID 29728103, 2018). "The apolipoprotein B mRNA editing catalytic polypeptide-like (APOBEC) family was first defined as an innate antiviral defense system, but the APOBEC3 subfamily (APOBEC3s) is now recognized as a major endogenous source of somatic mutagenesis in cancer." (PMID 41756300, 2026). "This nationally representative study indicates a negative linear correlation between serum ApoB and TT in adult American males without cancer." (PMID 38435750, 2024). "Among individuals without cancer, we explored the linear relationship between serum TT and serum apoB in various CVD, and visually depicted the relationship using a smooth curve fitting plot." (PMID 38435750, 2024). "In contrast, signature B correlated with COSMIC signature 1 (age of cancer diagnosis), and signature C correlated with COSMIC signature 13 (activity of the AID (activation-induced cytidine deaminase)/APOBEC (apolipoprotein B mRNA editing enzyme catalytic subunit) family)." (PMID 37051524, 2023). "For example, detected through next-generation sequencing, the apolipoprotein B mRNA-editing enzyme catalytic polypeptide-like, also known as APOBEC, has been reported to predict the efficacy of immunotherapy, not only in NSCLC but also in pan-cancer analysis." (PMID 36761426, 2022). "When CRP levels were added in the analysis, the apoB/apoA-I ratio, but not apoB levels, remained significantly related to cancer mortality (Q4 = HR: 1.17; 95% CI: 1.09–1.25)." (PMID 31936330, 2020). "In contrast, CRP levels were not able to predict cancer death after correction for apoB/apoA-I ratio." (PMID 31936330, 2020).
cancer (continued). "Furthermore, this is the first study that evaluated the predictive value of both apoB/apoA-I ratio and CRP levels in relation to cancer mortality." (PMID 31936330, 2020). "Although some of these genes can easily be linked with cancer biology (e.g. ATXN1 and PLXNC1), for others no such association has been reported (e.g. APOB)." (PMID 27014907, 2016). "However, after controlling for apoB, there was no longer an association of genetically predicted TG with all-cause mortality, CVD mortality, or non-CVD or cancer mortality." (PMID 38241044, 2024). "A group of DNA editing enzymes from human cells, called the apolipoprotein B mRNA-editing catalytic polypeptide-like 3 (APOBEC3), have been closely studied in research regarding the Human Immunodeficiency Virus (HIV) and later in connection to a vast number of cancer types." (PMID 37167010, 2023). "It is worth noting that IKBKB, APOB and MAPK9 are not only vital cholesterol metabolism regulation genes but are also often upregulated in cancer, which implies that the use of cholesterol-lowering drugs in HNSCC patients with the overexpression of these genes may be helpful." (PMID 37568192, 2023). "Finally, apoB/apoA-I, but not apoB, was a better predictor of cancer death than inflammatory markers (CRP) and other investigated traditional cardiometabolic risk factors." (PMID 31936330, 2020). "Similarly, after adjustment for the apoB/apoA-I in the Cox model, apoB could no longer predict cancer mortality (HR: 1.04; 95% CI 0.96–1.13)." (PMID 31936330, 2020). "However, in addition to identifying mutations in oncogenes and tumor suppressor genes, TCGA identified frequent mutations in albumin (ALB) and apolipoprotein B (APOB), which are not frequently mutated in other cancer types, suggesting that they may play unique roles in the development of HCC." (PMID 30429453, 2018).
tumor (85 papers, 2009 to 2025). "Apolipoprotein B mRNA editing enzyme catalytic polypeptide-like 2 (APOBEC2) is associated with nucleotide alterations in the transcripts of tumor-related genes which are contributed to carcinogenesis." (PMID 38166744, 2024). "The most potential miRNA associated with tumor progression of APOB was identified through correlation, expression, and survival analyses, specifically hsa-miR-21-5p, hsa-miR-9-5p, and hsa-miR-877-5p." (PMID 38310202, 2024). "The expression of apoB was significantly associated with the sigmoid and rectosigmoid tumor sites (p =0.001) and tumor size 3-5 cm (p =0.005)." (PMID 36864816, 2023). "Total cholesterol, LDL, and ApoB level show a linear association with the risk of neoplasms (both pnonlinear >0.05)." (PMID 37908181, 2023). "ApoB expression was significantly associated with the sigmoid and rectosigmoid tumor site (p =0.001) and tumor size of 3-5 cm (p =0.005)." (PMID 36864816, 2023). "For LDL/ApoB ratio, the third quantile (1.34–1.4) were associated with lowest risk of plasma neoplasm when compared with the lowest quartile and HR was 0.80 (95%CI, 0.69–0.92) in sex‐ and age‐adjusted model." (PMID 37908181, 2023). "We found that cholesterol profiles such as total cholesterol, HDL, LDL, apolipoprotein A, and apolipoprotein B were inversely correlated with the risk of plasma neoplasms." (PMID 37908181, 2023). "A high apoB expression was significantly associated with the sigmoid and rectosigmoid locations, and tumor sizes of 3-5 cm." (PMID 36864816, 2023). "The APOBEC3 family (apolipoprotein B mRNA editing enzyme catalytic polypeptide-like) was shown to induce tumor mutations through an aberrant DNA editing mechanism." (PMID 35740493, 2022). "Significant associations were observed between apoB expression with age (p value=0.036), tumour site (p value=0.048), bowel wall invasion (p value=0.035), Duke classification (p value=0.002), while 4HNE expression with tumour size (p value=0.029)." (PMID 36544136, 2022). "This study inspected the lipid metabolism status in circulation and tumor tissues simultaneously, and apoB/A was determined as a reliable marker that were associated with CRC long-term prognosis." (PMID 36713523, 2022). "APOB is a lipid metabolism regulator that is linked to carcinogenesis and tumour progression in the liver, lungs and other tissues." (PMID 31754644, 2019). "By contrast, apoB and apoA-I immunoreactivities were associated with lower tumor stage and better survival, respectively." (PMID 30173145, 2018). "Furthermore, mutational signatures associated with APOBEC (Apolipoprotein B mRNA Editing Enzyme Catalytic Subunit) activity have been shown to influence the tumor’s immune microenvironment and its response to immune therapies." (PMID 40003691, 2025). "ApoB is associated with tumour size and poor patient prognosis." (PMID 36998463, 2023). "Accumulating investigations revealed the potential mechanisms of these phenomena as follows: 1) According to several studies, ApoA-I is negatively associated with tumor-induced systemic inflammation, while elevated ApoB indicates a higher systemic inflammatory marker." (PMID 31956353, 2020). "Induction of hepatocellular lipid accumulation, oxidative stress, and the loss of a possible tumor suppressive activity of APOB are some of the hypothesis that have been raised." (PMID 30842500, 2019). "Only anti-apoB immunoreactivity was significantly associated with late tumor stage (P = 0.0371)." (PMID 30173145, 2018). "In the current study, extensive tumor necrosis was associated with a high APOB/APOA1 ratio, which could, at least partly, be related to the association between tumor necrosis and systemic inflammation." (PMID 28710487, 2017).